GGA3 (golgi associated, gamma adaptin ear containing, ARF binding protein 3)
Description:
Plays a role in protein sorting and trafficking between the trans-Golgi network (TGN) and endosomes. Mediates the ARF-dependent recruitment of clathrin to the TGN and binds ubiquitinated proteins and membrane cargo molecules with a cytosolic acidic cluster-dileucine (DXXLL) motif. Mediates export of the GPCR receptor ADRA2B to the cell surface. nvolved in BACE1 transport and sorting as well as regulation of BACE1 protein levels. Regulates retrograde transport of BACE1 from endosomes to the trans-Golgi network via interaction through the VHS motif and dependent of BACE1 phosphorylation. Modulates BACE1 protein levels independently of the interaction between VHS domain and DXXLL motif through recognition of ubiquitination. Key player in a novel DXXLL-mediated endosomal sorting machinery to the recycling pathway that targets NTRK1 to the plasma membrane (By similarity).
Synonyms: KIAA0154
Tractability: Small molecule: it has a binding pocket of medium quality. Antibody: UniProt places it where antibodies can reach, with high confidence. PROTAC: UniProt records ubiquitination sites on it; ubiquitination databases record sites on it; its protein half-life has been measured.
Gene: Protein-coding gene on chromosome 17 (75,236,595 to 75,262,363, reverse strand). Ensembl gene ENSG00000125447.
Subcellular location: Golgi apparatus, trans-Golgi network membrane; Endosome membrane; Early endosome membrane; Recycling endosome membrane
Subcellular location (Human Protein Atlas): Golgi apparatus
Pathways (Reactome):
Metabolism of proteins: Amyloid fiber formation
Signal Transduction: MET receptor recycling
Vesicle-mediated transport: TBC/RABGAPs
Gene Ontology:
Molecular function: cargo adaptor activity; protein binding; protein-containing complex binding; small GTPase binding; ubiquitin binding; phosphatidylinositol binding
Biological process: Golgi to plasma membrane protein transport; negative regulation of amyloid-beta formation; protein destabilization; protein localization to cell surface; protein targeting to lysosome; regulation of protein stability; Golgi to plasma membrane transport; intracellular protein transport; positive regulation of lysosomal protein catabolic process; endocytic recycling; vesicle-mediated transport
Cellular component: early endosome membrane; endosome membrane; Golgi apparatus; lysosome; protein-containing complex; trans-Golgi network; recycling endosome membrane; early endosome; recycling endosome
Genetic constraint (gnomAD): Loss-of-function variants: 54 observed, 67.92 expected, observed/expected ratio (o/e) 0.8, 90% interval 0.64 to 1. The upper end of that interval is the gene's LOEUF score, 1, which puts it in group 4 of 6, group 1 being the genes least tolerant of losing a copy. Missense variants: 950 observed, 889.06 expected, observed/expected ratio (o/e) 1.07, 90% interval 1.01 to 1.13. Synonymous variants: 408 observed, 377.51 expected, observed/expected ratio (o/e) 1.08, 90% interval 1 to 1.17.
Homologues: Orthologues: chimpanzee GGA3 (99% identical), macaque GGA3 (97% identical), dog GGA3 (87% identical), rat Gga3 (87% identical), mouse Gga3 (86% identical), guinea pig GGA3 (84% identical), pig GGA3 (83% identical), rabbit GGA3 (81% identical), zebrafish gga3b (55% identical), tropical clawed frog gga3 (54% identical), zebrafish gga3a (53% identical), Drosophila melanogaster Gga (25% identical), and 4 more. Paralogues in human: GGA1 (49% identical), GGA2 (39% identical), TOM1L2 (19% identical), TOM1 (18% identical), HGS (13% identical), TOM1L1 (12% identical), STAM (12% identical), STAM2 (11% identical), WDFY1 (9% identical), WDFY2 (9% identical).
Diseases named in the same sentence as GGA3 in open-access papers:
GGA3 is named in the same sentence as 11 diseases in open-access papers, as found by Europe PMC text mining. Sharing a sentence is not in itself a finding about the gene and the disease. The quoted sentences say what the papers report.
Alzheimer disease (3 papers, 2014 to 2017). A progressive, neurodegenerative disease characterized by loss of function and death of nerve cells in several areas of the brain leading to loss of cognitive function such as memory and language. "Decreased levels of GGA1 and GGA3 have been described for Alzheimer's disease." (PMID 28722658, 2017). "Golgi-localized γ-ear-containing ARF binding protein 3 (GGA3) is a monomeric clathrin adaptor that has been shown to regulate the trafficking of the Beta-site APP-cleaving enzyme (BACE1), which is required for production of the Alzheimer’s disease (AD)-associated amyloid βpeptide." (PMID 27192432, 2016). "In addition, the GAT domains of human GGA1 and GGA3, but not GGA2, bind ubiquitin and ubiquitinated proteins, and GGA1 and GGA3, but not GGA2, are depleted in the brains of patients with Alzheimer disease." (PMID 24637350, 2014).
Hypoglycemia (2 papers, 2012). A decreased concentration of glucose in the blood. "Furthermore, other than small size and perinatal hypoglycemia, the phenotypes were uninformative as to the basis for lethality of GGA2 mutant mice or GGA1/GGA3 double mutant mice." (PMID 23028818, 2012).
Stroke (2 papers, 2016 to 2018). Sudden impairment of blood flow to a part of the brain due to occlusion or rupture of an artery to the brain. "We have previously shown that BACE1 increases following caspase activation both in cellular models of apoptosis and in rodent models of stroke and TBI and proposed that caspase-mediated depletion of GGA3 is the underlying mechanism of BACE1 elevation." (PMID 29391027, 2018). "We also determined that depletion of GGA3 naturally occurs following caspase activation both in cellular models of apoptosis and in rodent models of stroke and traumatic brain injury (TBI)." (PMID 29391027, 2018). "We also determined that depletion of GGA3 naturally occurs following caspase activation both in cellular models of apoptosis and in rodent models of stroke and traumatic brain injury." (PMID 27192432, 2016). "Moreover, we have determined that GGA3 is depleted while BACE1 levels increase following experimental stroke and traumatic brain injury (TBI)." (PMID 27192432, 2016).
Anxiety (1 paper, 2016). Intense feelings of nervousness, tension, or panic often arise in response to interpersonal stresses. "Thus, the increased GABAergic transmission is a leading candidate mechanism underlying the reduced anxiety-like behaviors observed in GGA3 null mice." (PMID 27192432, 2016). "Thus, it is apparent that GGA3 deficient mice have elevations in phasic inhibition, increased number of inhibitory synapses events and reduced anxiety-like behaviors." (PMID 27192432, 2016). "We found that genetic deletion of GGA3 results in novelty-induced hyperactivity and decreased anxiety-like behaviors." (PMID 27192432, 2016). "We report here that GGA3 deletion results in novelty-induced hyperactivity and decreased anxiety-like behaviors." (PMID 27192432, 2016). "Thus, we performed a behavioral analysis of GGA3 null mice and found that GGA3 deletion results in novelty-induced hyperactivity and decreased anxiety-like behaviors." (PMID 27192432, 2016).
breast carcinoma (1 paper, 2021). "GGA3 mediates Met RTK recycling from Rab4-positive endosomes suggesting the possibility that members of the GGA family might influence SorLA-regulated RTK trafficking in HER2-positive breast cancer cells." (PMID 33420373, 2021).
cognitive decline (1 paper, 2026). "The PirB-CTF/GGA3 interface represents a promising therapeutic target for mitigating trafficking deficits and cognitive decline in neurodegenerative disorders." (PMID 42231420, 2026).
metastatic cancer (1 paper, 2020). A carcinoma which has spread from the original site of growth to another anatomic site. "MRNAs PRKCD, PRKAR1A, BTG2 competed with lncRNA RP11-408O19.5 for the same miRNAs (miR-15a-5p, miR-15b-5p, miR-16-5p, miR-195-5p) in primary cancer; lncRNA RP11-408O19.5 competed with GGA3 for miR-15b-5p, miR-16-5p, and miR-195-5p in metastatic cancer." (PMID 33614509, 2020).
tumor (3 papers, 2016 to 2022). "Similarly, expressions of both GGA1 and GGA3 were higher in some tumor regions than in non-tumor regions, but the increases were not statistically significant." (PMID 29358589, 2018).
cancer (2 papers, 2018 to 2020). A tumor composed of atypical neoplastic, often pleomorphic cells that invade other tissues. "However, because the present data also indicated that the protein expressions of GGA1 and/or GGA3 were also increased in some cancer tissues, relative amounts of GGA1, 2, and 3 could determine the EGFR stability." (PMID 29358589, 2018).
GGA3 also shares sentences with these, for which no sentence is quoted: amyloid (1 paper); brain injury (1).